CRP (C-reactive protein)
Diseases named in the same sentence as CRP in open-access papers (continued):
Sharing a sentence is not in itself a finding about the gene and the disease.
synovitis (98 papers, 2005 to 2025). Inflammation of a synovial membrane. "For synovitis, differences were only found in the 2nd MCP, while seropositivity status and DAS-28 CRP score were associated with synovitis in this joint, both in GS and PD." (PMID 36052337, 2022). "Both ESR and CRP were also associated with UltraSonography (US) which are signs of active synovitis." (PMID 36532039, 2022). "The univariate analyses showed associations for MRI synovitis and tenosynovitis with CRP (p < 0.01), SJC28 (p ≤ 0.01), patient-reported flare (p < 0.0001), pain (p ≤ 0.001), and PGA (p < 0.05)." (PMID 32014018, 2020). "In summary, a re-weighted DAS28 equation including only SJC28 and CRP was more closely associated with US-detected synovitis than definitions that also included TJC28 and GHVAS." (PMID 30824919, 2019). "A score based on SJC28 and CRP alone demonstrated stronger associations with synovitis and radiographic progression than the original DAS28 and should be considered in research on pathophysiological manifestations of early RA." (PMID 30824919, 2019). "To date, there are limited data on the association between circulating calprotectin, CRP and ultrasound-verified synovitis." (PMID 28832684, 2017). "For complete CR stifles, the following factors were significantly associated with Histologic Synovitis VAS: Synovial CRP (SR = 0.44, P = 0.02), and Histologic Synovitis Grade (SR = 0.62, P = 0.0003)." (PMID 28575001, 2017). "The synovitis score was significantly associated with CRP level (β = 0.10, P = 0.007), indicating that each 1 mg/L increase in CRP level resulted in a 0.10 increase in synovitis score." (PMID 24721160, 2014). "A total of 57% of knees with synovitis are associated with elevated concentrations of the inflammatory biomarker serum C-reactive protein." (PMID 22122951, 2011). "CRP-based DASs were more closely associated with synovitis than ESR-based counterparts." (PMID 30824919, 2019). "The synovitis scores were associated with CRP levels (P = 0.007) and joint tenderness (P = 0.026)." (PMID 24721160, 2014). "External replication and validation with imaging-based endpoints (e.g., ultrasound or MRI synovitis) will be essential to confirm the comparative utility of calprotectin and CRP in longitudinal RA monitoring." (PMID 41515559, 2025). "In RA calprotectin has emerged as a promising serum biomarker of inflammation, showing a strong correlation with ultrasound-detected synovitis and treatment response, even in patients with normal CRP levels." (PMID 41515559, 2025). "A correlation between infective triggers and higher CRP at diagnosis, faster response to therapy, and milder shoulder synovitis was found in these patients." (PMID 40508840, 2025). "This coincided with an improvement in synovitis, as well as reductions in erythrocyte sedimentation rate and C-reactive protein levels." (PMID 39093755, 2024). "In hand OA patients, after 12 weeks of colchicine treatment, CRP and ultrasound synovitis grade showed little improvement." (PMID 39775222, 2024). "HIMRISS scores, including BME score and synovitis were also significantly with CRP, ESR and disease activity scores of BASDAI and ASDAS ((p < 0.01)." (PMID 36935744, 2023). "A study conducted on 76 patients with psoriatic arthritis revealed that late-onset forms were more inflammatory with an increase in ESR and CRP, more synovitis, and edema of the hands and/or feet." (PMID 37273389, 2023). "Previous studies have shown that approximately half of RA patients with normal CRP levels have histological signs of synovitis, and almost three-quarters of patients in remission show inflammation within the tissues based on DAS28-CRP." (PMID 38203588, 2023). "Joint effusion and B-mode synovitis prevailed in male (p < 0.00001; p < 0.0001) and CRP + (p = 0.001; p < 0.00001) patients." (PMID 36743676, 2022). "PsA patients with subclinical synovitis and high CRP level had a higher number of joints showing subclinical synovitis." (PMID 37034375, 2022).
synovitis (continued). "In this early UA cohort study, we confirmed that higher VEGF values were statistically significantly associated with higher levels of CRP, ESR, number of swollen joints, and higher scores of synovitis and PD seen on US." (PMID 35744097, 2022). "Briefly, CRP + individuals and males had significantly more frequently joint effusion (p = 0.001 and p < 0.00001, respectively) and B-mode synovitis (p < 0.00001 and p < 0.0001, respectively)." (PMID 36743676, 2022). "To conclude, in our study, we confirmed that elevated VEGF levels were statistically associated with poor RA prognosis markers (positive RF and anti–CCP, ESR and CRP values, swollen joints count) and changes seen on US (synovitis, PD score, erosions grade)." (PMID 35744097, 2022). "It is also said that calprotectin is superior to CRP for predicting synovitis, with a positive correlation between the two (r = 0.556)." (PMID 34458672, 2021). "Two separate models of regression analysis, which used the PD US synovitis as a dependent variable, were calculated with calprotectin and CRP." (PMID 34386702, 2021). "We included in multivariate models those variables resulting in a significant prediction in univariate analysis, excluding the number of tender joints, likely correlated with VAS pain, and CRP, which correlates to ultrasound-detected synovitis." (PMID 34198963, 2021). "Another study detected clinically active joints by PD-US in 32 JIA patients, and observed that PD-US synovitis is more sensitive than ESR or CRP in identification of active disease." (PMID 31778437, 2019). "This study found that TJC28, SJC28, DAS28, ESR, CRP, synovitis, tenosynovitis, and BME were significantly lower in RA remission period than that in the active period." (PMID 29970124, 2018). "Histologic Synovitis Grade was weakly correlated with the following factors: Serum CRP (SR = 0.32, P = 0.09), Serum ICTP (SR = -0.36, P = 0.06), and Synovial:Serum ICTP (SR = 0.36, P = 0.06)." (PMID 28575001, 2017). "The multivariate regression analysis showed that calprotectin is a better predictor of the CDAI score and PD US synovitis than CRP." (PMID 28832684, 2017). "We have previously reported even stronger correlations between circulating serum calprotectin and ultrasound synovitis and demonstrated that calprotectin is a better predictor of ultrasound synovitis than conventionally used CRP." (PMID 28832684, 2017). "Histologic Synovitis VAS was weakly correlated with the following factors: Serum CRP (SR = 0.35, P = 0.06) and Synovial:Serum ICTP (SR = 0.31, P = 0.10)." (PMID 28575001, 2017). "Histologic Synovitis Grade was weakly correlated with the following factors: Synovial CRP (SR = 0.33, P = 0.09)." (PMID 28575001, 2017). "In a third cluster, Synovial:Serum CRP was positively correlated with several histologic markers of inflammation, including Histologic Grade, Histologic Synovitis VAS score, TRAP+ Macrophage Grade, and CD3+ T Lymphocyte Grade." (PMID 28575001, 2017). "We found severity of stifle synovitis assessed by synovial CRP and radiographic synovial effusion and osteophytosis was elevated in the CR stifle at diagnosis, when compared with the contralateral partial CR stifle, similar to previous work." (PMID 27575050, 2016). "Synovial IL-6 is also correlated with serum CRP, suggesting that serum CRP reflects synovitis in humans with OA, although these parameters were only weakly correlated in this report." (PMID 27575050, 2016). "Patients with early persistent arthritis had significantly higher levels of CRP than patients with resolving synovitis, mirroring the increase observed in systemic 11β-HSD1 activity in the early persistent group." (PMID 25971255, 2015). "Since sonographic synovitis predicts erosion better than swollen joint count, C-reactive protein and erythrocyte sedimentation rate, US should be considered a promising treatment target in RA patients with FM." (PMID 25738587, 2015).
synovitis (continued). "Secondary endpoints included repeated clinical assessments with DAS28(CRP), and assessments of osteitis and synovitis by the RAMRIS method." (PMID 25504080, 2014). "There were significant correlations between the CRP and the MRI tenosynovitis, MRI synovitis, and bone marrow edema (p = 0.002, p = 0.02, and p = 0.03), respectively." (PMID 23354165, 2013). "A higher CRP at presentation was unexpectedly protective of having persistent synovitis throughout the first year (P = 0.05)." (PMID 19796386, 2009). "A substantial proportion of PsA patients may exhibit clinically evident synovitis or axial inflammation despite normal CRP levels, particularly in cases with predominant enthesitis or oligoarticular involvement." (PMID 40572738, 2025). "The model that better described (AUROC 0.854) a patient with a diagnostic shift comprised higher frequency of bilateral gleno-humeral synovitis, bilateral PD signals on shoulders (any site), higher values of CRP, WBC, PLT and haemoglobin, longer time to obtain remission." (PMID 37498353, 2023). "However, when the thresholds of stringent remission are satisfied, as in the case of SJC and CRP ≤ 1, the probability of ultrasound-detectable synovitis is low." (PMID 37500945, 2023). "When a JA patient has more than 10 joints involved, accompanied by synovitis and elevated CRP levels or ESR, RA can be diagnosed according to the 2010 American College of Rheumatology (ACR)/European Alliance of Association for Rheumatology RA classification criteria." (PMID 36169251, 2022). "Adjusting for BMI, CRP was associated with radiographic knee osteophyte score (p=0.002), while CRPM was associated with synovitis of the knee (p=0.017), synovitis of multiple joints (p=0.008), and macrophage marker CD163 in serum (p=0.009) and synovial fluid (p=0.03)." (PMID 34465395, 2021). "Higher baseline pain, CRP and the presence of ultrasound-detected synovitis might help identify those patients for whom a more intensive monitoring and treatment escalation could be useful." (PMID 34198963, 2021). "Patients with positive rheumatoid factor (RF) and/or anticyclic citrullinated peptide (anti-CCP) and/or C-reactive protein (CRP) are known to be at increased risk of developing worse prognosis of erosive arthritis, the main clinical manifestation of which is synovitis." (PMID 35126351, 2021). "Separate logistic regression analysis models for calprotectin and CRP to predict PD synovitis." (PMID 34386702, 2021). "However, individual components of the DAS28 such as CRP, ESR, and SJC28 have been found to be associated with imaging‐detected synovitis suggesting that these markers are the most relevant measures for treatment response." (PMID 30311271, 2018). "Moreover, multiple regression analysis showed that calprotectin is a better predictor of PD US synovitis than CRP." (PMID 28832684, 2017). "Additionally, we found that CRP levels in serum and synovial fluid reflect severity of synovitis in both the partial CR and complete CR stifles." (PMID 28575001, 2017). "Synovial CRP was correlated with histologic synovitis in the complete CR stifles." (PMID 28575001, 2017). "Synovial:Serum CRP was correlated with histologic synovitis in partial CR stifles." (PMID 28575001, 2017). "We have shown that calprotectin might be a more sensitive tool for assessing joint inflammation and a better predictor of ultrasound synovitis than conventionally used C-reactive protein (CRP)." (PMID 27832086, 2016). "However, the baseline level of CRP in patients with early synovitis that persisted was higher than that in patients whose synovitis resolved." (PMID 25971255, 2015). "An enhanced angiogenic response rather than proinflammatory cytokines or systemic inflammation biomarkers (CRP, ESR) might underlie subclinical synovitis." (PMID 24398122, 2014).
synovitis (continued). "Patients with active synovitis had higher DAS28-C reactive protein (P = 0.023), DAS28-ESR (P = 0.06), simplified disease activity score, SDAI (P = 0.064), and only 12% were taking oral glucocorticoids (≤5 mg/day) compared with 40% of patients without active synovitis (P = 0.044)." (PMID 24398122, 2014). "Elevated ESR and CRP with synovitis might be found in patients with pachydermoperiostosis, yet it is fairly rare to note a two-fold elevation of ESR and a 10-fold elevation of CRP." (PMID 24330652, 2013). "In the cohort of patients with established RA, these additional analyses confirmed the exclusive association of CRP levels with synovitis, without differences in any other parameters, once again suggesting that standard clinimetrics seems unable to pick up ongoing synovitis in established RA." (PMID 31785084, 2020). "Therefore, we consider the 2C CRP-based model the most appropriate measure of global synovitis." (PMID 30824919, 2019). "Moreover, we found that serum calprotectin might be a better predictor of ultrasound-determined synovitis than CRP." (PMID 27832086, 2016). "Correlations between synovial MSC lubricin secretion and clinical parameters, including age, CRP, WBC, numerical rating scale for knee pain, synovial redness, synovial hyperplasia, and Krenn’s synovitis score, were assessed." (PMID 41299580, 2025). "All included FDRs were examined by MSUS for assessing the presence of subclinical synovitis; ESR and CRP were also measured." (PMID 38443806, 2024). "Cluster analysis identified a subgroup of older patients, with lower CRP, WBC, PLT and Hb, lower PD signal or peripheral synovitis who had a higher persistence in PMR diagnosis, suffered from more flares and took more GCs." (PMID 37498353, 2023). "SLC16A3 mRNA expression positively correlated with the histological grade of synovitis (CD3, CD20, CD69 and CD138 infiltration) and the disease activity score (DAS28 ESR and CRP)." (PMID 37304267, 2023). "Another study showed that the tocilizumab group had lower levels of CRP and disease activity score–28 joints (DAS28)-CRP than the adalimumab group; however, the ultrasound-based synovitis score was similar in the two groups." (PMID 36430392, 2022). "In detail, joint effusion was significantly more frequent in CRP + patients in the talo-navicular joints (p = 0.0181), and B-mode synovitis was more frequent in the MTP I (p = 0.021) and MTP III joints (p = 0.0075) compared to the CRP- patients." (PMID 36743676, 2022). "In RA sera, VEGF and IL-6 levels were elevated in proportion to synovitis severity, correlating with conventional markers for disease activity, including ESR, CRP, and DAS28." (PMID 32461558, 2020). "Taken together, our data suggest that PlGF and VEGF, as angiogenic cytokines, are correlated with synovitis severity and disease activity in RA patients and that serum VEGF has a better value to represent treatment response than ESR and CRP." (PMID 32461558, 2020). "Furthermore, all patients included in this study, including those with normal CRP and in remission by DAS28-CRP, were reporting arthralgia in the joint biopsied, and therefore these individuals may be more likely to have synovitis than others with the same CRP/DAS28-CRP." (PMID 30123796, 2018). "For complete CR stifles, the following factors were significantly correlated with Histologic Synovitis Grade: Histologic Synovitis VAS (SR = 0.62, P = 0.0003) and Synovial CRP (SR = 0.44, P = 0.02)." (PMID 28575001, 2017). "Infliximab showed greater decrease from baseline in DAS28(CRP), DCE-MRI Ktrans of wrist and MCP synovium, and RAMRIS synovitis and osteitis at all visits compared with placebo (p<0.001)." (PMID 29236711, 2017). "In the cross-sectional analyses, we found a moderate to strong correlation of ultrasound measures such as the GS and PD synovitis scores with TJC, SJC, DAS28-ESR, DAS28-CRP, SDAI, CDAI, CRP and ESR." (PMID 28832684, 2017).
synovitis (continued). "Multivariate regression analysis was used to determine the predictive values of calprotectin, CRP and SJC for CDAI and PD US synovitis scores." (PMID 28832684, 2017). "After 12 months from RA diagnosis in the overall population there was a significant reduction of disease’s activity, as expressed by ESR, serum CRP levels, TJCs, SJCs and DAS28, and US synovitis and p-D score (all p-values < 0.001), as expected." (PMID 25887374, 2015). "Since sonographic synovitis predicts erosion better than SJC, CRP and ESR, US should be considered a promising treatment target in RA patients with FM." (PMID 25738587, 2015). "While there is often no detectable synovitis on a physical examination, a subset of patients have tenderness of multiple joints and elevated C-reactive protein (CRP)." (PMID 40078238, 2025). "We confirmed that CRP serum levels are not a biomarker of active synovitis in patients under anti-IL-6R therapy, as shown by previous reports." (PMID 35054349, 2022). "This absolute lack of correlation between CRP and inflammatory activity was also found when synovitis was measured by US in the present study." (PMID 35054349, 2022). "Synovial sphingomyelin (SM) correlated positively with the synovitis score but not with the ESR or CRP." (PMID 35169224, 2022). "PsC patients with subclinical synovitis had significantly higher CRP than patients without (p-value: 0.003)." (PMID 37034375, 2022). "A strong correlation between Anti-Carbamethylated Protein (CarP) antibody levels and both clinical and ultrasonographic activity was described (correlation between anti-CarP and DAS-28 (r=0.96), CRP (r=0.97), ESR (r=0.97) and US power Doppler+synovitis with a Pearson coefficient >0.97)." (PMID 36532039, 2022). "Age, disease duration, treatment duration, DAS28, CRP, ESR, CCP, RF, synovitis score on GSUS, synovitis score on PDUS, tenosynovitis score on GSUS, tenosynovitis score on PDUS, 7-joint ultrasonic bone erosion, and total US7 scores were designated as variables X1-X14, respectively." (PMID 33394305, 2021). "Calprotectin, but not CRP, had a significant contribution to clarifying PD synovitis as a dependent variable in the logistic regression models (p = 0.024 in model 1 for calprotectin and p = 0.630 in model 2 for CRP)." (PMID 34386702, 2021). "When the patients with normal CRP levels were assessed (n = 34), serum calprotectin levels were found significantly higher in those with PD synovitis than those without PD synovitis (96.3 ± 45.7 vs 59.2 ± 44.7, respectively, p=0.024)." (PMID 34386702, 2021). "The other serum concentrations were not correlated with effusion-synovitis volume (hs-CRP; p = 0.181, IL = 6; p = 0.203, adiponectin; p = 0.437)." (PMID 32704147, 2020). "On univariate analysis, a good or moderate EULAR response was significantly associated with swollen joint count (≥ 7), early treatment (started within 3 months after the date of first reported synovitis), ESR, CRP level, and HAQ-DI ≥ 1 (p < 0.05 for all comparisons)." (PMID 31730497, 2019). "Foot tenosynovitis was predictive (OR 2.55, 95% CI 1.01–6.43), independent of BME and synovitis (OR 3.29, 95% CI 1.03–10.53), but not independent of CRP and number of swollen joints (OR 2.14, 95% CI 0.77–5.95)." (PMID 30764871, 2019). "Hand tenosynovitis was also predictive independent of BME and synovitis (OR 3.99, 95% CI 1.64–9.69) and independent of CRP and swollen joints (OR 2.36, 95% CI 1.04–5.38)." (PMID 30764871, 2019). "At baseline, DAS28(CRP) correlated significantly with synovial Ktrans in the wrist (Pearson correlation coefficient (90% CI) = 0.39 (0.19–0.55)) and MCPs (0.36 (0.16–0.53)) and with RAMRIS-synovitis in the wrist (0.29 (0.08–0.47)) and MCPs (0.54 (0.37–0.67))." (PMID 29236711, 2017). "Synovitis scores and FOIAS were compared with the cJADAS10, physician’s global assessment of disease activity, functional disability scores (CHAQ), and laboratory parameters (ESR, CRP)." (PMID 29041986, 2017).